LEP (leptin)
Diseases named in the same sentence as LEP in open-access papers (continued):
Sharing a sentence is not in itself a finding about the gene and the disease.
Obesity (continued). "Intriguingly, the mammalian target of rapamycin is also one of the signal mediators of obesity-related factors, such as leptin, adiponectin, and inflammatory cytokines, through the AMPK pathways." (PMID 36292657, 2022). "Due to increased serum leptin levels in allergic rhinitis, they propose a possible connection of allergic rhinitis to obesity." (PMID 35844529, 2022). "This was in line with animal studies, which showed that both obesity and leptin reduced orthodontic tooth movement in mice and rats by affecting osteoclastogenesis." (PMID 36142638, 2022). "Considering the involvement of neural IL1R1 in celastrol-dependent anti-leptin resistance it is reasonable to postulate that IL1R1 is complicatedly implicated in the protection of celastrol against obesity through both central and peripheral mechanisms." (PMID 36009315, 2022). "Leptin is a hormone secreted by adipose tissue and its levels are increased in individuals with obesity in a BMI-dependent manner." (PMID 35960996, 2022). "Current research indicates that obesity is positively correlated with levels of the adipokine, leptin." (PMID 36584083, 2022). "The full effect of leptin in regulating obesity is governed by the central nervous system and particularly important is the hypothalamus." (PMID 35388304, 2022). "In satiety-induced obesity state, increased leptin cannot result in more energy consumption, which is considered as “leptin resistance”." (PMID 36531958, 2022). "This suggests that obesity is generally the result of an insensitivity to high circulating levels of leptin, also known as leptin resistance." (PMID 36411386, 2022). "Meanwhile, some reports showed that the status of obesity systemic low-grade inflammation was reported to elevate the levels of cytokines, chemokines, and leptin in the serum." (PMID 36551211, 2022). "Obesity increases the liberation of leptin and other adipokines due to an increase in adipose tissue volume." (PMID 35326592, 2022). "The molecular mechanisms of the relationship between obesity and breast cancer involve estrogens, insulin, leptin, adiponectin, and inflammatory cytokines." (PMID 35223490, 2022). "Critically important obesity-related factors such as glucose, cortisol, leptin, and adiponectin have been studied in this study." (PMID 36499541, 2022). "The endocrine system is influenced by fetal development, but recent studies have identified leptin and insulin resistance as key endocrine changes in obesity and related metabolic disorders." (PMID 36397166, 2022). "In contrast, biological evidence shows that children with low birth weight have a higher concentration of plasma leptin which increases their obesity risks." (PMID 36589948, 2022). "Breast milk contains adipokines such as resistin and leptin and is known for its protective effect against obesity and insulin resistance." (PMID 35225882, 2022). "These pellets have a statistically significant (p<0.05) impact on obesity biomarkers by increasing adiponectin and decreasing leptin, free fatty acid and insulin concentrations relative to HFD control." (PMID 35910274, 2022). "Obesity has a strong relationship with DM, and excessive fat tissue will lead to the secretion of more leptin." (PMID 36619557, 2022). "Elevated leptin levels provide evidence for a central nervous system-mediated mechanism of obesity in SPG11." (PMID 36432490, 2022). "Ghrelin causes excessive eating and obesity by stimulating food intake, whereas leptin reduces excessive eating and obesity by inhibiting eating." (PMID 36096730, 2022). "Ghrelin modulates the central appetite regulatory network, especially neuropeptide γ, and ghrelin interacts with a variety of adipocytokines, such as leptin and insulin, and plays an important role in the pathological process of obesity." (PMID 35069014, 2022).
Obesity (continued). "Given the growing proportion of obesity in pregnancy, future studies should focus on elucidating possible biological mechanisms involved, such as inflammation and leptin signaling." (PMID 36307528, 2022). "Celastrol has multiple biological pharmacological activities, which can not only inhibit inflammation and immune response, but can also enhance the sensitivity of the brain to leptin and inhibit hunger and obesity." (PMID 36371217, 2022). "Pterostilbene and resveratrol strongly modulate ghrelin and leptin levels while these metabolism‐ and obesity‐related proteins profoundly alter the expression of TRH and TRH‐like peptides." (PMID 35875858, 2022). "EGFRs are also closely involved in obesity—experimental studies have shown that EGFRs are transactivated by leptin, a hormone of an elevated concentration in patients with obesity/metabolic syndrome." (PMID 35144605, 2022). "There is compelling evidence that circulating nutritional factors (lipids, glucose), hormones (insulin, insulin-like growth factor, leptin), and cytokines (interleukins, tumor necrosis factor), among others, connect obesity and cancer." (PMID 36074318, 2022). "This study is a systematic review and a meta-analysis based on the relationship between leptin and asthma during obesity." (PMID 36613991, 2022). "Leptin concentrations in the peripheral blood of obese people is proportional to the degree of obesity, and hyper-leptinemia promotes steatosis with or without NAFLD." (PMID 36294318, 2022). "We further performed stratified analysis to determine the association between LEP/LEPR polymorphisms and breast cancer risk according to obesity indicators including BMI and WHR." (PMID 35223490, 2022). "Combining resistance and aerobic exercise training also improved the cardiometabolic indicators of older men with obesity along with a reduction in leptin levels." (PMID 36225863, 2022). "Obesity can increase proliferation through a number of pathways, with perhaps leptin taking a central role." (PMID 36038791, 2022). "VF can inhibit uterine smooth muscle contraction, resulting in obesity/metabolic syndrome in women with weak uterine contractions, with a stronger effect than traditional adipokines such as leptin." (PMID 35113808, 2022). "Leptin is an anti-obesity protein and its action is mainly mediated by the activation of its Ob-R receptor in neuronal cells." (PMID 36512575, 2022). "Nonetheless, obesity‐related dose of leptin elevated not only the release of IL‐6 and IL‐17, but also IL‐5 and IL‐13 by CD4+ T cells in lean‐derived cell cultures from patients." (PMID 35734271, 2022). "Of note, a prominent increase in plasma leptin was also reported in the late-onset obesity cases of 6-month-old Oxt KO mice." (PMID 36281647, 2022). "Initial evidence suggests a dominant role for adipokines such as leptin, changes to nutrient availability and alterations to the gut microbiota in controlling changes to B cell function in patients living with obesity." (PMID 35960996, 2022). "As this is one of the first studies to describe the predictive potential of leptin and adiponectin regarding post-treatment weight gain in children with obesity, further research is required to confirm these findings." (PMID 35769076, 2022). "Recently it was suggested that increased levels of leptin secreted by obesity altered adipose stem cells induced the EMT and CSC reprogramming of MCF7, BT20, HCC1806, and TU-BcX cancerous cells through expression of Serpine1, SNAI2, IL6, TWIST1, and PTGS2." (PMID 36077676, 2022). "Of note, the most studied adipokine leptin plays an essential role in regulating immune system function, promoting an obesity-related low-grade inflammation state." (PMID 35631195, 2022). "By transcriptionally controlling the expression of the gut-derived hormone Cck, ATF5 is able to positively regulate serum leptin levels, thus stimulating satiety and preventing obesity." (PMID 36516750, 2022).
Obesity (continued). "The role of leptin resistance in the progression of obesity and inflammation has been reported earlier." (PMID 36033946, 2022). "The present study undoubtedly proves that the expression of leptin, visfatin and chemerin in the human liver is altered in overweight and obesity." (PMID 35549673, 2022). "This was notable because Cox-4 expression stimulated by leptin seems to be abrogated in obesity, as shown in an in vitro study of human myotubes." (PMID 36144258, 2022). "Chronic inflammation and elevated leptin levels, which are common in obesity, reduce the secretion of ZAG in AT." (PMID 35406070, 2022). "Obesity stimulates several cellular processes that reduce leptin signaling which is known as cellular leptin resistance and increase the amount of weight gain prompted by environmental factors and genetics." (PMID 35655598, 2022). "Leptin is a peptide hormone known to play a critical role in the meta-inflammatory state observed in obesity." (PMID 36291602, 2022). "The consequences of this leptin resistance are an increase in fat mass and gaining weight, worsening obesity." (PMID 36359273, 2022). "Concentrations of sLEP-R are differentially regulated in metabolic disorders, such as type-1 diabetes mellitus or obesity, and can, therefore, enhance or reduce leptin sensitivity." (PMID 36289764, 2022). "The biological network analysis showed that HJJPD plays a role in treating leptin resistance in simple obesity by acting on multiple targets in the JAK2-STAT3 pathway via various components." (PMID 35529938, 2022). "Leptin modulates appetite and metabolic rates through hypothalamic orexigenic and anorexigenic factors and prevents excessive weight gain and obesity in humans and animals." (PMID 34934398, 2022). "Studies including high-fat diet (HFD) or ob/ob mice (leptin knockout mice, a classic model to study obesity in animal models) have all presented increased galectin-1 in the adipose tissue." (PMID 36295832, 2022). "In the Spanish subjects, those with obesity, hypertension, type 2 diabetes, hypercholesterolemia, and metabolic syndrome had higher leptin concentrations than their normal-weight counterparts." (PMID 35406000, 2022). "In the case of obesity, the occurrence of which is determined by numerous factors, estimating the influence of leptin, one of the breast milk components, is particularly challenging." (PMID 35684517, 2022). "In this sense, previous studies by our group revealed that leptin treatment during the suckling period prevents diet-induced obesity later in life." (PMID 35684076, 2022). "Together, these data suggest that IL-6 released due to exercise overlaps with the anorexigenic effect of leptin in the context of diet-induced obesity." (PMID 36452038, 2022). "Further research should be targeted toward discovering the exact mechanisms in which body weight and obesity affects leptin signaling to participate in the formation and propagation of endometriotic lesions." (PMID 36140261, 2022). "In obesity, transport mechanisms are saturable and become insensitive due to higher levels of leptin." (PMID 35334918, 2022). "Obese participants exhibited significantly higher leptin levels, positively correlating with obesity and IR markers." (PMID 35334929, 2022). "In a pioneering study, Liu and co-workers (2015) uncovered that celastrol is a leptin sensitiser and exerts robust anti-obesity properties." (PMID 36009315, 2022). "In this way, it is possible to highlight the mechanisms of action of leptin, resistin, adiponectin, aromatase, IGF-1, and pro-inflammatory cytokines in cancers to characterize new associations between obesity and other neoplasias." (PMID 36262532, 2022). "Leptin has been found to be an important mediator of the obesity-related pro-inflammatory state that contributes to metabolic disorders." (PMID 36010082, 2022).
Obesity (continued). "The inability of leptin to induce activation of its specific signaling pathways, especially under endoplasmic reticulum stress, leads to the leptin resistance observed in obesity." (PMID 36512575, 2022). "Leptin levels in white adipose tissue and plasma are related to the energy store, such that leptin increases in obesity and decreases during fasting." (PMID 35198097, 2022). "The association of adipokines (leptin, adiponectin), hs-CRP, and IL-6 with well-known cardiovascular risk factors (lipid profile, diabetes regulation, obesity, physical activity) in children and adolescents with T1D is this study’s main purpose." (PMID 36010052, 2022). "It was concluded that the obesity altered microenvironment conferred enhanced metastatic potential upon TNBC cells through leptin-mediated pathways." (PMID 36077676, 2022). "This manifested as obesity and increased circulating leptin levels, accompanied by leptin resistance." (PMID 35355566, 2022). "The present results indicate that regulation of leptin secretion is involved in the anti‐obesity effect of PG." (PMID 35154693, 2022). "Of important note, leptin has been already started to be recognized as a factor capable of affecting developmental programming in other contexts than obesity." (PMID 36855701, 2022). "Leptin was detected by cloning of the obesity (ob) gene and is involved in satiety, food intake energy adequacy, and regulation of body weight." (PMID 36077676, 2022). "In chronic low-grade inflammation and obesity, leptin stimulates production of IL-6 and TNF-α and reduces adiponectin." (PMID 35008925, 2022). "Obesity alters hormones such as adiponectin and leptin, affecting all levels within the hypothalamic-pituitary-gonadal axis." (PMID 36320802, 2022). "To identify the molecular linking between TNF-α and leptin under the state of obesity, we firstly investigated the effects of leptin and TNF-α on the GSIS function in INS-1E cells." (PMID 35198097, 2022). "At the same time, less sleep time leads to reduced leptin secretion, increased brain intestinal hormone secretion, and increased appetite, all of which lead to obesity." (PMID 36684986, 2022). "The etiology and pathways involved in obesity, particularly in leptin resistance-induced obesity, is yet to be elucidated." (PMID 35937803, 2022). "In another study, dapagliflozin was shown to downregulate circulating leptin levels in patients with type 2 diabetes and class 3 obesity during a 1-year administration." (PMID 36499312, 2022). "For example, leptin-deficient rodents and humans, which are generally characterized by obesity, impaired glucose tolerance, insulin resistance as well as hyperinsulinemia, can be normalized by leptin therapy." (PMID 34996484, 2022). "Among the different adipokines liberated by adipose tissue in obesity, leptin has been postulated to contribute to breast cancer tumorigenesis and progression." (PMID 36591465, 2022). "Leptin is strongly correlated with maternal weight and BMI and serves as a biomarker of maternal and fetal obesity." (PMID 36359305, 2022). "Individuals with obesity were shown to have reduced ghrelin (1/3–1/2 time lower), and increased leptin levels (2–8 times higher), compared to normal-weight controls." (PMID 35634372, 2022). "Altered expression of leptin and its receptor, which results in leptin resistance, is critical in obesity and its related complications." (PMID 35563103, 2022). "In our study, in addition to the result that leptin was found to positively correlate with all obesity markers, OB subjects had higher insulin and HOMA-IR values compared to NW subjects, and a positive correlation was seen between leptin, insulin and HOMA-IR." (PMID 36355134, 2022). "In this sense, different studies have analyzed leptin levels and leptin/leptin receptor expressions as a probable bridge between obesity and lymphomas." (PMID 36555171, 2022).
Obesity (continued). "We should observe if leptin antagonists would exacerbate obesity while energy catabolism is corrected in this population." (PMID 35369060, 2022). "One of them is the influence of OSA combined with obesity on levels of ghrelin, leptin, and obestatin, i.e., neuropeptides strongly related to body energy homeostasis." (PMID 35407646, 2022). "In brain, obesity leads to an inflammatory process that impairs both insulin and leptin signaling in the hypothalamus, exacerbating obesity (Jais and Brüning, 2017)." (PMID 35112705, 2022). "Recent evidence showed that ER stress and abnormal UPR activation in the hypothalamus are involved in central leptin/insulin resistance in obesity and T2DM." (PMID 35103058, 2022). "Melatonin also inhibits leptin secretion and ameliorates leptin resistance, which accompanies obesity." (PMID 36501110, 2022). "Taken together, our results reinforce the perinatal programming role of leptin in preventing obesity-related disorders; in this case, preventing the appearance of an MONW phenotype, which had not been previously reported." (PMID 35684076, 2022). "The role of leptin in the obesity-related hypertension pathogenesis appears to be a result of the circulatory system, renal activity & modulation and sympathetic nervous system (SNS) activation and can be prevented by adrenergic blockade drugs." (PMID 35334523, 2022). "Due to the relationship between thyroid hormones and blood lipid levels with some neurotransmitters, it is recommended to study the effects of A. garcinii extract on dopamine and leptin levels and obesity gene expression." (PMID 35614888, 2022). "Increased placental nutrient delivery secondary to increased leptin levels contributes to fetal overgrowth in offspring of mothers with obesity." (PMID 36189369, 2022). "Leptin plays an important role in the increased T cell dysfunction and PD-1 expression seen with obesity." (PMID 35752704, 2022). "Stimulation of isolated B cells from lean individuals with leptin reduced pAMPK levels to those observed in obesity." (PMID 35960996, 2022). "Obesity in childhood induces the secretion of adipocytokines such as leptin, TNF-α, and IL-6, and slows the secretion of adiponectin, which causes insulin resistance." (PMID 35742443, 2022). "Further obesity-related genes include MC4R, peroxisome proliferator-activated receptor gamma (PPAR-G), and both adipokine-encoding genes (LEP and ADIPOQ)." (PMID 35565885, 2022). "The secretion of adipokines (leptin and adiponectin) and cytokines (C-reactive protein, TNF, IL-6, IL-8) driven by adipose tissue in obesity can alter the expression and secretion of factors associated with angiogenesis in the primary tumor." (PMID 36014894, 2022). "In numerous populations and age groups, the effect of LEP and LEPR polymorphisms on the risk of obesity has been well-documented." (PMID 35886710, 2022). "Of the multiple potential mechanisms linking obesity and autoimmunity, the strongest link has been shown for leptin, a hormone secreted at high levels from obese white adipose tissue." (PMID 36479348, 2022). "In human studies, two hormones—ghrelin and leptin—are closely related to the cardiovascular effects of obesity." (PMID 35327129, 2022). "The M1 phenotype, characteristic for obesity, is known to produce higher levels of adipokines, and, in turn, adiponectin (and leptin) is capable of regulating obesity-induced inflammation in OA, by modulating immune activity." (PMID 35204546, 2022). "Children and adolescents with obesity tend to have higher leptin levels and lower adiponectin levels." (PMID 35057485, 2022). "Research has shown that patients with sarcopenic obesity have higher serum leptin levels than those with non- sarcopenic obesity." (PMID 35250869, 2022). "With the known link between obesity, insulin resistance and EC, adipokines and hormones such as leptin have become the focus of intense investigation." (PMID 36230588, 2022).